SNORA44 (small nucleolar RNA, H/ACA box 44)
Synonyms: ACA44
Gene: Small nucleolar RNA gene on chromosome 1 (28,580,381 to 28,580,512, reverse strand). Ensembl gene ENSG00000273544.
Gene Ontology:
Biological process: RNA processing
Cellular component: nucleolus
Homologues: Orthologues: chimpanzee SNORA44 (100% identical), rabbit SNORA44 (89% identical), pig SNORA44 (88% identical), mouse Snora44 (85% identical), rat LOC120093958 (84% identical), rat LOC120094889 (84% identical), rat LOC120095413 (84% identical), rat LOC120100370 (84% identical), rat LOC120097977 (83% identical), rat LOC120098681 (83% identical), rat LOC120093959 (80% identical), rat LOC120096789 (67% identical), and 21 more.
Diseases named in the same sentence as SNORA44 in open-access papers:
SNORA44 is named in the same sentence as 2 diseases in open-access papers, as found by Europe PMC text mining. Sharing a sentence is not in itself a finding about the gene and the disease.
SNORA44 shares sentences with these, for which no sentence is quoted: cancer (1 paper); diffuse large B-cell lymphoma (1).